C4orf46 (chromosome 4 open reading frame 46)
Synonyms: RCDG1; LOC201725
Tractability: PROTAC: ubiquitination databases record sites on it.
Gene: Protein-coding gene on chromosome 4 (158,666,675 to 158,672,255, reverse strand). Ensembl gene ENSG00000205208.
Subcellular location: Cytoplasm
Subcellular location (Human Protein Atlas): Cytosol
Gene Ontology:
Molecular function: protein binding
Cellular component: cytoplasm; cytosol
Genetic constraint (gnomAD): Loss-of-function variants: 8 observed, 6.25 expected, observed/expected ratio (o/e) 1.28, 90% interval 0.73 to 1.89. That is too few expected variants to judge how well the gene tolerates losing a copy. Missense variants: 151 observed, 136.26 expected, observed/expected ratio (o/e) 1.11, 90% interval 0.97 to 1.27. Synonymous variants: 51 observed, 52.69 expected, observed/expected ratio (o/e) 0.97, 90% interval 0.77 to 1.22.
Homologues: Orthologues: chimpanzee C4H4orf46 (100% identical), macaque C5H4orf46 (97% identical), pig C4orf46 (88% identical), dog C15H4orf46 (84% identical), mouse 4930579G24Rik (82% identical), rat C2h4orf46 (82% identical), tropical clawed frog C4orf46 (48% identical).
Diseases named in the same sentence as C4orf46 in open-access papers:
C4orf46 is named in the same sentence as 5 diseases in open-access papers, as found by Europe PMC text mining. Sharing a sentence is not in itself a finding about the gene and the disease. The quoted sentences say what the papers report.
metastatic tumors (1 paper, 2023). "In general, overexpression of the C4orf46, C9orf40, C17orf67 and C21orf58 gene of thymoma correlates with tumor immune cell infiltration and gene expression levels of C1orf162, C16orf54 and CXorf21 correlate with immune cell infiltration in many primary and metastatic tumors." (PMID 37373333, 2023).
renal carcinoma (1 paper, 2023). A carcinoma arising from the epithelium of the renal parenchyma or the renal pelvis. "A renal cancer associated gene, renal cancer differentiation gene 1 [RCDG1, originally called as chromosome 4 open reading frame 46 (C4orf46)] is significantly down regulated in RCC tissues as compared to normal adjacent tissues." (PMID 37970211, 2023).
tumor (2 papers, 2019 to 2023).
C4orf46 also shares sentences with these, for which no sentence is quoted: renal cell carcinoma (1 paper); thymoma (1).